CCDC146 (coiled-coil domain containing 146)
Description:
Essential for sperm flagellum biogenesis and male fertility.
Synonyms: KIAA1505; MBO2; SPGF94
Tractability: PROTAC: ubiquitination databases record sites on it.
Gene: Protein-coding gene on chromosome 7 (77,122,434 to 77,329,533, forward strand). Ensembl gene ENSG00000135205.
Subcellular location: Cytoplasm, cytoskeleton, microtubule organizing center, centrosome, centriole; Cytoplasm, cytoskeleton, flagellum axoneme; Cytoplasm, cytoskeleton, cilium basal body; Midbody
Gene Ontology:
Molecular function: protein binding; protein-containing complex binding
Biological process: spermatid development; manchette assembly; sperm axoneme assembly; sperm flagellum assembly
Cellular component: axoneme; centriole; centrosome; ciliary basal body; midbody; sperm flagellum; cytoskeleton; sperm head-tail coupling apparatus
Genetic constraint (gnomAD): Loss-of-function variants: 61 observed, 81.49 expected, observed/expected ratio (o/e) 0.75, 90% interval 0.61 to 0.93. The upper end of that interval is the gene's LOEUF score, 0.93, which puts it in group 3 of 6, group 1 being the genes least tolerant of losing a copy. Missense variants: 798 observed, 922.27 expected, observed/expected ratio (o/e) 0.87, 90% interval 0.82 to 0.92. Synonymous variants: 313 observed, 325.17 expected, observed/expected ratio (o/e) 0.96, 90% interval 0.88 to 1.06.
Homologues: Orthologues: chimpanzee CCDC146 (99% identical), macaque CCDC146 (97% identical), pig CCDC146 (88% identical), dog CCDC146 (88% identical), rabbit CCDC146 (83% identical), rat Ccdc146 (77% identical), mouse Ccdc146 (77% identical), tropical clawed frog ccdc146 (51% identical), zebrafish ccdc146 (35% identical). Paralogues in human: CFAP58 (17% identical).
Diseases named in the same sentence as CCDC146 in open-access papers:
CCDC146 is named in the same sentence as 13 diseases in open-access papers, as found by Europe PMC text mining. Sharing a sentence is not in itself a finding about the gene and the disease. The quoted sentences say what the papers report.
male infertility (2 papers, 2024). The inability of the male to effect fertilization of an ovum after a specified period of unprotected intercourse. "This study allowed us to identify and validate the involvement of a new candidate gene in male infertility, CCDC146." (PMID 38441556, 2024). "We used these lines to address the hypothesis that CCDC146 deficiency leads to MMAF and male infertility." (PMID 38441556, 2024).
asthma (1 paper, 2020). "Among ten hub DEGs identified for the asthma-COPD, nine DEGs including SPAG6, C7orf57, SYTL3, LRRC48, TEKT3, CCDC146, CETN2, CCDC19, and C14orf45 were identified as the novel genes." (PMID 31952466, 2020).
Chlamydia (1 paper, 2018). "In summary, we found a novel interaction between a C. trachomatis Inc protein (CT288) and a host cell protein (CCDC146), which is recruited to the periphery of the inclusion membrane and thus could play an important role during Chlamydia host cell infection." (PMID 30094225, 2018).
Chlamydia infections (1 paper, 2018). "Therefore, while this remains to be directly analyzed, it is possible that the CT288-CCDC146 interaction and recruitment of CCDC146 to the periphery of the inclusion are relevant in the general context of Chlamydia infections." (PMID 30094225, 2018).
Infertility (1 paper, 2024). "As such, we have identified bi-allelic truncating mutations in CCDC146 in two unrelated infertile patients displaying MMAF." (PMID 38441556, 2024). "Taken together, these elements strongly suggest that mutations in the CCDC146 gene could be responsible for the infertility of these two patients and the MMAF phenotype." (PMID 38441556, 2024). "From a cohort of 167 infertile patients suffering from multiple morphological abnormalities of the flagellum (MMAF), pathogenic bi-allelic mutations were identified in the CCDC146 gene." (PMID 38441556, 2024). "Ccdc146 KO mice are infertile and KO sperm exhibit a typical multiple morphological abnormalities of the flagellum (MMAF) phenotype." (PMID 38441556, 2024).
thyroid cancer (1 paper, 2024). "This hypothesis is supported by the fact that CCDC146 is reported to be downregulated in thyroid cancer." (PMID 38441556, 2024).
cancer (2 papers, 2022 to 2024). A tumor composed of atypical neoplastic, often pleomorphic cells that invade other tissues. "Therefore, it would be interesting to monitor aging in Ccdc146 KO mice and to study their life expectancy and cancer rates compared to WT mice." (PMID 38441556, 2024).
infection (2 papers, 2018 to 2023). The state of being infected such as from the introduction of a foreign agent such as serum, vaccine, antigenic substance or organism. "CT288 was shown to interact with human centrosomal protein CCDC146 and is partially responsible for recruiting it to the inclusion membrane during infection, potentially playing a role in inclusion anchoring at the MTOC." (PMID 37155906, 2023). "To test if CT288 and CCDC146 could interact during infection, we infected HEK293T cells with C. trachomatis L2/434 harboring pCT288-2HA." (PMID 30094225, 2018). "Therefore, CT288 modulates the recruitment of EGFP-CCDC146692−955 to the periphery of the inclusion, which also suggests it could control the function of CCDC146 at the inclusion membrane during infection." (PMID 30094225, 2018).
tumor (1 paper, 2025). "Moreover, gene expression analysis showed that the expressions of KRT8 and S100A16 were significantly increased in tumor tissues, while the expressions of COL4A3, SMAD9, MAP3K8 and CCDC146 were decreased." (PMID 41239716, 2025).
CCDC146 also shares sentences with these, for which no sentence is quoted: Obesity (2 papers); diabetic neuropathy (1); heart failure (1); influenza (1).